IL2 (interleukin 2)
Diseases named in the same sentence as IL2 in open-access papers (continued):
Sharing a sentence is not in itself a finding about the gene and the disease.
tumor (continued). "However, recent preclinical studies have shown that other gamma-chain cytokines (such as IL-7 and IL-15) promote a less-differentiated T cell phenotype, resulting in longer persistence and better anti-tumor effects in comparison to IL-2." (PMID 34503109, 2021). "Tumor-bearing mice that were untreated or treated with IL-2 alone were used as controls." (PMID 34172810, 2021). "It increases IL2 and IFNɣ secretion by T cells that suppress tumor growth." (PMID 34795581, 2021). "Moreover, anti-IL-23 monoclonal antibody acts synergistically with targeted therapies or IL-2 to suppress tumor growth and metastases, supporting the tumor-promoting activity of IL-23." (PMID 34680308, 2021). "Next, we studied whether adenoviruses coding for two cytokines enhancing anti-tumor T-cell activity (TNFa and IL-2) could induce responses in the aPD-1 refractory tumors." (PMID 34367166, 2021). "Moreover, CD4+ Th1 T-lymphocytes destroy tumor cells also trhough the secretion of cytokines and chemokines, especially interleukin 2 (IL2) and interferon-gamma (IFNγ), which help the recruitment of further NK cells, CD8+ T-lymphocytes and macrophages." (PMID 33920423, 2021). "Strikingly, siRNA-mediated silencing of SIGLEC15 in SN increased the secretion of anti-tumor cytokines, including IL2, IFN-γ, and TNF-α, suggesting that inhibiting SIGLEC15 expression in SNs could restore T cell function." (PMID 34722496, 2021). "However, 2 out of 3 animals treated with the unarmed virus still had visible tumors at the end of the experiment, while all 3 animals in the wt IL-2 group were tumor free." (PMID 34084172, 2021). "However, attempts to induce anti-tumor T cell responses using systemic agonism with agents such as anti-CD137 antibodies and high dose interleukin-2 (IL-2) are associated with significant risk of toxicity." (PMID 34584159, 2021). "In fact, in pre-clinical and clinical studies, adenoviruses armed with cytokines such as GMCSF, TNFa and IL-2 conferred improved anti-tumor response, with enhanced effector CD8+ T and helper CD4+ T cell trafficking into tumors, when compared to their unarmed versions." (PMID 34084172, 2021). "ICI therapy can activate T cells, and this may subsequently result in higher IL-2 production by CD4+ T-helper cells in the tumor microenvironment." (PMID 34076745, 2021). "We discovered that KIRS2/Dap12 receptor infused with 4-1BB co-stimulation domain could enhance anti-tumor efficacy by remarkably increasing the production of pro-inflammatory interleukin-2 (IL-2), especially when co-cultured with antigen-positive tumor cells." (PMID 34703879, 2021). "In addition, TRegs activated in the tumor context are extremely respondent to low concentrations of their main activator, IL-2, due to the acidity of CD25." (PMID 34944856, 2021). "Moreover, IL-7R expressing effector memory T cells derived from naive T cells possess high affinity to IL-2 and thereby enhance the survival of themselves in tumor microenvironment." (PMID 34575268, 2021). "This study suggested that cryosurgery generates the most favourable immune-regulatory response for abscopal tumours and activation of anti-tumour immune cells, and increased secretion of pro-inflammatory cytokines such as IL-1β, IL-2, IL-6, IL-12β, IFN-γ and TNF-α." (PMID 34281259, 2021). "In addition, ARI2h cells expanded with IL-2, IL-15, or IL-15/IL-7 were injected into MM tumor-bearing mice to assess their in vivo efficacy." (PMID 34298748, 2021). "Indeed, tumor-infiltrating CD4+ T cells expressing IL2 were increased after TIGIT blocking monoclonal antibody (mAb) treatment in a head and neck squamous cell carcinoma mouse model." (PMID 34367161, 2021). "In addition, patients in the low-risk group had a higher expression level of cytokines in the tumor tissues, such as IL-2, IL-6, and IL-18, which was consistent with more infiltrating immune cells in the low-risk group." (PMID 34616734, 2021).
tumor (continued). "In addition, compared to auto-CD4+ T cells, AAA-CD4+ T cells produced 4-fold higher amounts of IL-2 transcripts at 24 h post-therapy, which led to more than a 100-fold higher concentration of IL-2 in the local tumor." (PMID 34625113, 2021). "Tryptanthrin effectively inhibited tumor growth in 4 T1 murine breast cancer model; modulated expression levels of nitric oxide synthase 1 (NOS1), COX-2, and nuclear factor kappa-B (NF-κB) in mouse tumor tissues; and regulated some factors such as IL-2, IL-10, and TNF-α in mice." (PMID 37789475, 2021). "In the same context, Interleukin 2 (IL-2) exerts significant anti-tumor activity." (PMID 34959371, 2021). "We observed the concomitant expression of anti-tumor factors (Il1b, Il13, Ccl7, Il2)." (PMID 34578328, 2021). "Besides targeting Treg cells and VEGF, we also used acetylsalicylic acid to modulate tumor endothelial FasL expression and low-dose IL-2, which supports in vivo tumor-specific T cell proliferation." (PMID 34572778, 2021). "We reason that this could be due to tumor cells of lymphoid origin expressing multiple activating ligands and/or high quantity of cytokines, such as IL-2, that rescue the dysfunctional phenotype of WASp-KO NK cells." (PMID 33621210, 2021). "Our results suggest that, under specific tumor contexts, therapies based on IL2 administration may favor tumor growth instead of just promoting immune T cell proliferation and survival." (PMID 33498681, 2021). "In addition, bispecific CP CAR-T cells secreted much higher IFN-γ and IL-2 expression against c-Met and PD-L1 positive tumor cells compared with other groups." (PMID 33777728, 2021). "Interestingly, vIL-2 virus was capable of stimulating the highest global relative expression of hamster IL-2 plus vIL-2 cytokines in the tumor microenvironment: mock (p<0.0001), virus backbone (p<0.0001), and wt IL-2 virus (p=0.026)." (PMID 34084172, 2021). "Indeed Muller and colleagues (2000) showed that the activation and function of tumor infiltrating immune cells (IL-2) was significantly perturbed in acidic conditions." (PMID 34268109, 2021). "Subsequently, transfection of tumor cells with genes coding for cytokines that promote antigen presentation (discussed later), activate T cells and APC or induce costimulatory molecules (IFNγ, IL-2, IL-4, IL-7, GM-CSF) were shown to increase tumor immunogenicity and elicit antitumor immunity." (PMID 33671123, 2021). "Therefore, creating an anti-tumor agonist of the IL-2 pathway with the desired biological activity, safety profile, and ideal drug-like properties remains an unmet need in the field." (PMID 34011961, 2021). "For future studies, it would be interesting to compare N-803 to the standard IL-2 co-administration with NK cell adoptive transfer for anti-tumor efficacy, to evaluate whether IL-2 can be replaced by N-803 to prevent Treg-expansion in cancer patients." (PMID 33140189, 2021). "For the activation of immune cells with MMP inhibition by MMST, CXCL-10 stimulated immune cells through polarization and activation of Type 1 T-helper cells, resulting in the enhanced paracrine secretion of IFN-γ and IL-2 to facilitate the anti-tumor efficacy of TMNPs + HT." (PMID 34959271, 2021). "It is assumed that interactions of IL-2Rα with IL-2 may stimulate the growth and proliferation of tumor cells and promote tumor aggressiveness." (PMID 33995947, 2021). "Tenascin-C has already been targeted by a recombinant antibody–cytokine fusion protein for delivery of IL-2 into tumours, and it may be that a similar approach could be used to deliver compounds to the pre-metastatic niche." (PMID 34564696, 2021). "Similarly, PTK7-CAR T cells produced a large amount of IFN-γ and IL-2, which is positively associated with the expression level of PTK7 on respective tumor cells." (PMID 34475869, 2021).
tumor (continued). "A phase I study enrolling 15 dogs with B-cell lymphoma tested a therapy with a combination of autologous tumor antigen-coated microbeads (large multivalent immunogen—LMI) with cytokine therapy including IL-2 and GM-CSF, following induction of remission with conventional chemotherapy." (PMID 34513964, 2021). "Remarkably, in a patient who cannot tolerate T cell activation (due to risk of graft failure), local injection of the potent T cell activator IL-2 was sufficient to maximize the anti-tumor immune response and did not cause any further toxicities." (PMID 34122442, 2021). "Although the cytotoxicity by UA ATC against tumor cells is lower compared to armed T cells, but may induce comparable levels of IL-2 (IL-2 in the culture supernatants of UA ATC and tumor cells ranges: 47-170 pg/ml)." (PMID 34290709, 2021). "In addition, metformin improves immune response by increasing CD8+ tumor-infiltrating lymphocytes and decreasing inflammatory chemokine production of IL-2, TNFα, and IFNγ." (PMID 34055551, 2021). "This functional test is also used in patients with MM or RCC undergoing IL-2 based immunotherapy to detect specific immune responses against selected tumor antigens and could represent a reliable biomarker of response to treatment." (PMID 34777395, 2021). "Furthermore, its combination with HSP70 vaccine induced a potent anti-tumor immunity by increasing the expression of Th1 cytokines, IL-2, and IFN-γ and decreasing transcription levels of IL-10, TGF-β, and Foxp3 in the tumor microenvironment." (PMID 34531847, 2021). "Additionally, recent evidence has shown CD4 T cells can acquire cytotoxic capabilities in the presence of IL-2 and mediate direct tumor cell killing." (PMID 34012443, 2021). "Immunohistochemistry performed on murine tumor sections revealed strong staining of tumor-associated CD3+ T cells, primarily consisting of CD8+ T cells, indicating that Alb-IL2 could induce effective adaptive immune responses." (PMID 34790830, 2021). "IL2 stimulates the proliferation and activation of immune cells with anti-tumor activity." (PMID 34521875, 2021). "Although activated CAR T cells produce cytokines, such as interleukin-2 (IL-2), production decreases after repeated exposure to tumor cells, and some cytokines that are important for T cell effector function, such as IL-12 and IL-15, are either produced at low levels are not at all by T cells." (PMID 34177932, 2021). "In addition to activated and memory T cells, several other immune cells also express CTLA-4 such as regulatory T cells (Tregs; which constitutively express CTLA-4) and tumor-infiltrating NK cells, and is induced on mouse NK cells upon IL-2 stimulation." (PMID 34531847, 2021). "Their tumor-permissive effect is achieved either by restraining the proliferation of tumor-specific effector cells or by limiting the secretion of IL-2 and IFN-γ owing to the expression of CTLA-4, glucocorticoid-induced tumor necrosis factor receptor (GITR), and Foxp3." (PMID 34831048, 2021). "Combination delivery of TGF-β inhibitor and IL-2 by nanoscale liposomal polymeric gels can deliver small hydrophobic molecular inhibitors and water-soluble protein cytokines in a sustained way to the tumor microenvironment to enhance tumor immunotherapy." (PMID 33628850, 2021). "The murine tumour cell line B16 divides at a rate of 24.9 h per cell division, slightly slower than ILC2s, while IL-2–sensitive, co-stimulated CD8+ T-cells have an impressive doubling time of 5.3 h56, essential to mount effective cellular responses against tumours or pathogens." (PMID 34112824, 2021). "To further investigate whether this phenomenon occurs in vivo, we examined tumor growth, lactate production, the population of activated cytotoxic T-cell, T cell caspase 3/7 activity, and T cell IL-2 production in A549 xenograft tumors." (PMID 34482375, 2021).
tumor (continued). "In mice, the combination of lenalidomide and elotuzumab was very effective in reducing tumor volume and increasing the infiltration of NK cells into the tumor microenvironment, an effect enhanced by IL-2 secreted by T cells and TNF-alpha produced by monocytes and macrophages." (PMID 34307150, 2021). "We aimed to expose whether host or tumor cells respond to IL-2-mediated cytokines for PD-L1 expression." (PMID 33986267, 2021). "The expression of the IL-2 Rα subunit on CD4+ regulatory T cells (Tregs) results in the preferential stimulation of these immunosuppressive cell types and is reported to limit the stimulatory effects of IL-2 on effector populations needed for anti-tumor responses." (PMID 34373459, 2021). "Notably, the expression of IL-2 mRNA in the CD44hi donor CD4+ T cells of the AAA-CD4+ group dramatically increased (7-fold) within the tumor 24 h after injection, relative to 4 h after injection, while IL-2 mRNA was not increased in the auto-CD4+ group." (PMID 34625113, 2021). "Additionally, IL7-Fc further enhanced anti-tumor responses that were induced by recombinant human IL2 in the same mouse model." (PMID 34440787, 2021). "IL-2 has an essential impact on the differentiation and proliferation of both regulatory and effector T cells, hence playing important roles in the tradeoff between anti-tumor tolerance and immunity." (PMID 33868318, 2021). "The ADCC induced by the cetuximab and IL-2 or IL-15 combination was more evident, since the combination reduced the xenograft tumor volume with an increase in infiltrating NK cells, whereas no significant induction of direct antiproliferative effects on the tumor was observed." (PMID 34207383, 2021). "The use of IL-2 to suppress immune responses is an extraordinary example of the same agent being used at different doses for opposing purposes, since high-dose IL-2 is used to promote anti-tumour responses in cancer patients." (PMID 35156097, 2021). "CIK cells are a mixture of cytotoxic T cells and natural killer (NK) cells separated from peripheral blood mononuclear cells and are cultured in vitro under treatment with cytokines such as IFN-γ, anti-CD3 antibody and IL-2 to promote their proliferation and anti-tumor activities." (PMID 33854960, 2021). "In order to investigate whether the Immunomodulatory mAbs induce tumor cell lysis through the activation of hPBMCs, we examined the release of Interleukin 2 (IL-2) and Interferon gamma (IFN-γ)." (PMID 34201082, 2021). "Furthermore, RHWPs also markedly increased the levels of TNF-α, IFN-γ, and IL-2 in the sera of tumor-bearing mice, and activated immune cells such as lymphocytes, NK cells, and macrophages, thereby inducing tumor cell apoptosis." (PMID 33921554, 2021). "Trivalent CAR T cells displayed increased IFN-γ and IL-2 secretion after tumor recognition compared to monovalent and bivalent constructs, and the trivalent CAR therapy was able to eliminate nearly all tumor cells in an orthotopic patient-derived xenograft (PDX) mouse model." (PMID 33746981, 2021). "This study demonstrated that the 99mTc-IL2 scan might provide a tool for the in vivo assessment of tumor-infiltrating IL-2R-positive cells, which could be extremely beneficial for patient selection with unlabeled IL2 immunotherapy." (PMID 34445532, 2021). "On the one hand, therapeutic proteins like recombinant IL2 or immune checkpoint inhibitors may activate tumor-specific CD8+ cytotoxic T lymphocytes, thus facilitating the killing of malignant cells in vivo." (PMID 33796916, 2021). "This may be due to tumor cells affected the activation of NK cells by inhibiting IL-2, IFN-γ, and TNF-α secretion, thus rendering them inept." (PMID 35046996, 2021). "IL-2 promotes NK cell survival, differentiation, cytolytic activity and cytokine production and therefore may enhance NK anti-tumour activity in conjunction with OV therapy." (PMID 34888493, 2021).
tumor (continued). "Additionally, increased expression of miR-28 on murine T cells decreased their exhaustion state in B16-F10 tumor-bearing mice, as shown by the recovery of their capacity to secrete IL-2 and TNF-α." (PMID 34830805, 2021). "Tumor-associated macrophages (TAMs) may play a dual role in neoplasms: They can both kill tumor cells after activation by IL-2, interferon, and IL-12." (PMID 34885171, 2021). "For example, the lipid-coated biodegradable hollow mesoporous silica nanoparticles with co-encapsulation of ATRA, doxorubicin and interleukin-2 (IL-2) showed great potential for developing a viable strategy to remodel the tumour immune microenvironment and achieve enhanced antitumour effect." (PMID 33805295, 2021). "Tumor infiltrating lymphocytes (TILs) are isolated from a tumor resection piece, then activated and expanded in vitro prior to being reinfused into the patient with systemic IL-2 stimulation after preparative lymphodepletion." (PMID 34359621, 2021). "In addition, a pre-clinical study comparing CAR T cells secreting different γ-chain-cytokines (IL-2, IL-7, IL-15, and IL-21) found increased anti-tumor activity with all the cytokines tested, but effects were mediated through different mechanisms." (PMID 33746981, 2021). "Moreover, it inhibits the secretion of cytokines interleukin-1 (IL-1) and IL-2, promotes T cell apoptosis, mediates tumor immune escape, and promotes tumor growth." (PMID 34249750, 2021). "Furthermore, they reported that NK cells pre-activated with TKD and IL-2 recognize mHSP70 on tumor cells." (PMID 33815422, 2021). "A final explanation for the slight decrease in tumor tracer uptake during ICI treatment might becompetition with endogenous IL-2 for binding to the IL-2R." (PMID 34076745, 2021). "Experiments on animal models elucidated the potent role of AGP in increasing the antibody-mediated cellular toxicity, mitogen-induced bone marrow cell proliferation, increased production of IL2, and anti-tumor cytokine IFNγ in both tumor-bearing as well as healthy animal models." (PMID 34795581, 2021). "In later studies by this same group, further analysis on the immune effects of this FAP-targeting DNA vaccine found a shift in the immune environment towards the more anti-tumor Th1 polarization with an increase in expression in the Th1 cytokine profile including IL-2 and IL-7." (PMID 34200702, 2021). "Therefore, we also suggested that the APC cells of tumor-bearing mice were activated by engulfing the co-expression plasmid vaccine and then up-regulated the levels of IL-2 and IFN-γ both in serum and genital secretions." (PMID 34635698, 2021). "The generation of TIL products is possible through the use of high dose IL-2 in tumor digests." (PMID 33815400, 2021). "IL-2, an important mediator of inflammation and the immune response in a variety of infectious diseases, can enhance host immunity and inhibit the growth of tumours and parasites." (PMID 34256821, 2021). "In fact, many tumor therapies targeting IL-15 and IL-2 have shown positive therapeutic effects." (PMID 34497605, 2021). "Similarly, a variety of different ILs, such as IL-2, IL-15, IL-27, and IL-6, play an important role in tumor microenvironment and immunotherapy." (PMID 34497605, 2021). "We used this version of IL2 with the goal of maximizing tumor-over-healthy organs exposure." (PMID 33796916, 2021). "Importantly, we found that virus that had transduced tumor was functional and able to express its transgenes IL-2 and TNF-a." (PMID 32920593, 2021). "Besides, in addition to maintaining the potent antitumor properties of IL-2, histamine was found to constrain tumor growth in a rat model of prostate adenocarcinoma." (PMID 34439898, 2021). "To assess which factors present in the conditioned medium may regulate GITRL expression, we determined release of a panel of tumor-associated cytokines, namely TGFβ, IFNγ, IL-10, TNF and IL-2." (PMID 33538861, 2021).